EGF (epidermal growth factor)
Diseases named in the same sentence as EGF in open-access papers (continued):
Sharing a sentence is not in itself a finding about the gene and the disease.
breast carcinoma (continued). "For example, 111In-labelled block copolymer micelles (BCMs) modified with EGF to target EGFR-positive breast cancer cells were assembled by incorporating a DTPA-polyethylene glycol (PEG)-b-polycaprolactone (PCL) block polymer into these micelles." (PMID 31659527, 2019). "Interactions between HER2 and H3K4me1 were observed using PLA and silencing of HER2 significantly reduced the number of immunofluorescent foci observed in the nuclei of the EGF-treated breast cancer cells." (PMID 31747426, 2019). "To further investigate the hindering effects of iEFs on EGF-promoted migration of breast cancer cells, we blocked Akt signaling, an important downstream effector of EGFR phosphorylation." (PMID 31428691, 2019). "SK2 has been previously shown to localize predominantly to the plasma membrane in MDA-MB-453 breast cancer cells, where it was found to be required for migration of these cells towards epidermal growth factor." (PMID 30250299, 2019). "We found that iEFs downregulated EGFR activation and also prevented formation of actin-rich filopodia in breast cancer cells in the presence of EGF." (PMID 31428691, 2019). "Cell proliferation induced by recombinant epidermal growth factor (rEGF) produced in both normal and breast cancer cells, an increased tyrosine phosphorylation of H1, more evident in tumoral cells (MCF7) compared to normal cells (MCF10)." (PMID 31816600, 2019). "iEFs inhibited EGFR (Epidermal Growth Factor Receptor) activation, prevented formation of actin-rich filopodia, and hindered the motility of EGF-treated breast cancer cells." (PMID 31428691, 2019). "CBD can also inhibit the growth and metastasis of breast cancer cells through the epidermal growth factor (EGF)/epidermal growth factor receptor (EGFR) and protein kinase B (AKT)/mTOR/4EBP1 signaling pathways." (PMID 31349651, 2019). "To confirm our finding from sequencing analysis we separately treated SKBR3 and BT474 (another HER2-positive breast cancer cell line) with EGF and conducted RT-qPCR." (PMID 30736768, 2019). "Pyk2 colocalizes with cortactin to invadopodia of breast cancer cells and regulates EGF–induced cortactin phosphorylation through Src‐mediated Abl‐related gene (Arg) activation, leading to actin polymerization and breast cancer cell invasion." (PMID 31368612, 2019). "EGFR signaling has been known to decrease 3H-Thymidine incorporation in EGF treated breast cancer cells, including SKBR3 cells." (PMID 30736768, 2019). "RNA-sequence and ChIP-sequence for H3K18ac and H3K27ac (Histone H3 lysine K18 and K27 acetylation) were conducted following an Epidermal Growth Factor (EGF) treatment time course in HER2+ breast cancer cells, SKBR3." (PMID 30736768, 2019). "Collectively, results from both migration assays (MBDM and modified Transwell) clearly demonstrate that iEFs selectively hinder the EGF-promoted motility of breast cancer cells." (PMID 31428691, 2019). "Next, the cells were detached and re-plated on non-adherent cell culture plates in serum-free medium containing EGF and B27—conditions known to promote the development of breast cancer tumorspheres." (PMID 31812165, 2019). "We also show that iEFs potently decrease migration speeds and migration numbers of metastatic breast cancer cells with EGF(+)." (PMID 31428691, 2019). "Smurf1 induced degradation of RhoA promotes EGF (epidermal growth factor) induced breast cancer cell migration and invasion." (PMID 31248165, 2019). "In this study, we used Next Generation Sequencing (NGS) technologies to determine the fluctuations in gene expression following EGF treatment of SKBR3 (HER2+ breast cancer cells)." (PMID 30736768, 2019). "Collectively, EGF/EGFR/AJAP1 axis controled breast cancer tumor progression and metastasis by mediating the β-catenin nuclear transactivation." (PMID 31171012, 2019).
breast carcinoma (continued). "Signaling activated by epidermal growth factor (EGF) triggers the cortactin-mediated maturation of invadopodia that are required for invasion by different aggressive tumor cells, including breast cancer cells." (PMID 31514269, 2019). "Decreased EGF expression is beneficial for the prevention of breast cancer because EGF is a potent mitogen for normal and neoplastic mammary epithelial cells." (PMID 30864639, 2019). "Pro-migratory effects of antiparallel iEF(+)/EGF(−) treatment of malignant breast cancer cells were completely abrogated by inhibiting Akt phosphorylation." (PMID 31428691, 2019). "Over 2,000 HER2 binding sites are found in both breast cancer cell lines after EGF treatment, and according to pathway analysis, these binding sites were enriched near genes involved in protein kinase activity and signal transduction." (PMID 31747426, 2019). "In conclusion, we identified a novel signaling pathway of EGF-mediated up-regulation of PN-1 in breast cancer cells, which requires cascade activation of EGFR/PKCδ/MEK/ERK/EGR1, which was crucial for breast tumor metastasis and BCSC stemness." (PMID 31501409, 2019). "On the other hand, the use of a MAP kinase inhibitor U0126 protected breast cancer cells from EGF-induced Mcl-1 overexpression." (PMID 31404252, 2019). "The increased lamellipodia formation and cell migration of human breast cancer cells MDA-MB-231 by EGF were accompanied by Cdk5 activation and increased phosphorylation of ADD1 at T724." (PMID 31548578, 2019). "Since S100A6 consistently demonstrated higher levels in all three lines we tested, we sought to determine the role of S100A6 in HER2-overexpressing breast cancer cells and in EGF/EGFR cell signaling through siRNA knockdown experiments." (PMID 30736768, 2019). "By implication, EGF(+)/iEF(+) transformed MCF10As to closely match the EGF(−) breast cancer cell migratory phenotype." (PMID 31428691, 2019). "Further experiments were conducted to evaluate the ability of ChPL to synergistically interact with an EGF inhibitor (AG1478) to inhibit MAPK/ERK signaling in breast cancer cells." (PMID 31404252, 2019). "The ’Rho-Associated Protein Kinase 1’ (ROCK1) is known to play an important role in the EGF-induced formation of stress fibers in keratinocyte and to be involved in the cofilin pathway in breast cancer." (PMID 31438847, 2019). "Our H3K18ac and H3K27ac ChIP-seq data, demonstrates for the first time that the chromatin landscape has been assessed in an EGF treatment time course of HER2+ breast cancer cells." (PMID 30736768, 2019). "We were able to identify not only well known general toxic compounds like detergents and proteasome and topoisomerase inhibitors, but also compounds leading to proliferation like EGF in breast cancer cell lines." (PMID 31552418, 2019). "In breast cancer, the prognostic value of EGF is also a matter of debate while most studies point toward a positive correlation between serum EGF levels and prognosis." (PMID 31358848, 2019). "It has been found that EGF-induced breast cancer cell invasion is MICAL1-dependent, which forms complexes with RAB35." (PMID 31019460, 2019). "In the present study, US-induced cavitation of SonoVue® microbubbles (SV) was used with the intention of enhancing the delivery of an exemplar liposomal formulation, 111In-EGF-LP-Dox, for chemo-radionuclide therapy targeted to breast cancer cells." (PMID 31534505, 2019). "On the other hand, MSCs have been shown to promote mammosphere formation partially via the epidermal growth factor (EGF)/EGF receptor/Akt pathway to regulate self-renewal through cytokine networks in breast cancer cells." (PMID 30705410, 2019). "The SKBR3 breast cancer cell line was treated with vehicle or EGF for 3 hours and total RNA was collected for RNA-seq." (PMID 31747426, 2019).
breast carcinoma (continued). "Investigating the status of RSK1, RSK2, and RSK3 revealed that besides RSK2, RSK1 is also translocated to the nucleus after EGF stimulation in two breast cancer cell lines tested." (PMID 30126195, 2018). "Functional validation of PTPN5 in tamoxifen sensitive, tamoxifen resistant and TNBC cells shows that activation of PTPN5 suppressed the EGF-induced MAPK signaling pathway in breast cancer cells." (PMID 29590203, 2018). "Crosstalk between TGFβ and the epidermal growth factor (EGF) is a well-documented case during breast cancer EMT." (PMID 30463358, 2018). "For example, knockdown of ANXA2 in breast cancer cells resulted in a more epithelial phenotype, in which cells were unable to undergo EGF-induced EMT." (PMID 29568351, 2018). "On the contrary, BAPTA-AM had opposite effects on two EMT transcription factors- it increased levels of TWIST1, but decreased the EGF- induced expression of SNAI1, a factor associated with decreased relapse-free survival in women with breast cancer." (PMID 30034631, 2018). "Further, experimental evidence in breast cancer cell lines suggests that cross-talk between signaling pathways of steroids and growth factors such as EGF or IGF-1 is necessary to induce cell growth and proliferation." (PMID 30400783, 2018). "In this study, we showed that NgBR knockdown attenuates tamoxifen resistance in MCF-7 and T47D breast cancer cells by inhibiting EGF-stimulated phosphorylation of ERα." (PMID 30208932, 2018). "NgBR knockdown with siRNA attenuates EGF-induced phosphorylation of ERα and restores the sensitivity to tamoxifen in ERα-positive breast cancer cells." (PMID 30208932, 2018). "Approximately 7% of cell-bound EGF translocates into the cell nucleus during first 4 h of in vitro incubation of [111In]-DTPA-EGF with MDA-MB-468 human breast cancer cells; this index doubles by the 24th hour of incubation." (PMID 30210340, 2018). "EGF is considered an important growth factor in enhancing various effector functions of breast cancer cells." (PMID 29590154, 2018). "In 2011, the Lin group demonstrated that EGF stimulation of breast cancer and epidermoid carcinoma cells leads to CARMA3-dependent NF-κB activation." (PMID 30158935, 2018). "The interaction of Cas with Src promotes tamoxifen resistance of breast cancer cells through the EGF signaling pathway." (PMID 30460082, 2018). "As a tyrosine kinase substrate, tyrosine phosphorylation of WBP2 at Try192 and Try231 stimulated by epidermal growth factor (EGF) can cause disturbances of cell proliferation regulation and induce tumorigenesis in breast cancer cells." (PMID 29497031, 2018). "Treatment of breast cancer cells with EGF induced the internalization of NKP from the cell membrane to the cytoplasmic compartment." (PMID 29590154, 2018). "Collectively, these data suggest that imatinib and GNF-5, and to a lesser extent nilotinib, can inhibit EGF-mediated actin barbed end generation at invadopodia of breast cancer cells." (PMID 29774130, 2018). "It encodes myoferin, a plasma-associated protein involved in Ca2+-channel formation, important in myoblast functioning and involved in EGF-induced cell migration in breast cancer." (PMID 30103445, 2018). "As previously reported, melittin exerts an antitumor effect on non-small-cell lung cancer cells and suppresses EGF-induced cell motility and invasion in breast cancer cells." (PMID 29854840, 2018). "Previous work has shown paracrine loop signaling between tumor cells and macrophages, where epidermal growth factor (EGF) from macrophages induced by colony stimulating factor 1 (CSF-1) from tumor cells contributes to breast cancer cell motility and invasion." (PMID 29636067, 2018). "Our lab has previously demonstrated that dormant micrometastases can be stimulated to outgrowth in an ex vivo microphysiological system model for breast cancer metastasis to the liver by using a combined stimulus of EGF and LPS." (PMID 29763460, 2018).
breast carcinoma (continued). "Further, chelation of intracellular calcium with BAPTA-AM reduced EGF-induction of cell migration in the MDA-MB-468 breast cancer cell line." (PMID 30034631, 2018). "In our study, EGF shifted the epithelial-like MDA-MB-468 breast cancer cells to a mesenchymal phenotype and WJ460 compromised this ability." (PMID 30213946, 2018). "Previous studies have shown that there is paracrine loop signaling between breast cancer cells and macrophages involving colony stimulating factor 1 (CSF-1) produced by tumor cells and epidermal growth factor (EGF) production by macrophages." (PMID 29636067, 2018). "Our lab has previously shown that EGF stimulation of dormant breast cancer cells can drive outgrowth from dormancy in an ex vivo microphysiological system model for breast cancer metastasis to the liver." (PMID 29763460, 2018). "Skp2 SCF complex is an E3 ligase that mediates Akt ubiquitination and activation upon EGF stimulation, leading to the promotion of breast cancer development." (PMID 30413706, 2018). "Accordingly, breast cancer cells undergoing EMT in response to TGFβ secrete EGF, which signals the activation of the focal adhesion kinase that mediates cytoskeletal remodeling that promotes cell motility." (PMID 30463358, 2018). "On the other hand, some evidence related EGF as a key inducer of angiogenesis, invasiveness of tumor cells in—in vitro and in vivo studies—with cells obtained from mouse mammary cancer." (PMID 30322002, 2018). "EGF is a growth factor that signals proliferation and migration in breast cancer, and is present as an autocrine stimulatory factor in most all aggressive mammary carcinomas." (PMID 29763460, 2018). "For example, it has been shown that the treatment of MCF7 mammary tumor cells with epidermal growth factor (EGF) promotes an increase in the expression of sphingosine kinase 1, an enzyme required for cell proliferation and migration." (PMID 30149660, 2018). "Consistently, our data also showed that HER2, but not HER3, is involved in the heterodimerization with EGFR and in the regulation of EGF‐induced Akt signaling in HER2‐positive breast cancer cells." (PMID 28632938, 2017). "In summary, we propose a signaling mechanism by which EGF up-regulates the expression of CCR1 through the AKT-mTOR-STAT3 axis in MDA-MB-231 breast cancer cells." (PMID 29212252, 2017). "The forkhead box C1 (FOXC1) transcription factor, an important prognostic biomarker specific for BLBC, has been shown to be induced by EGF and is critical for EGF effects in breast cancer cells." (PMID 28629477, 2017). "These include the up-regulation of tTG protein and/or mRNA levels downstream of growth factors and cytokines, such as EGF in breast cancer cells, TGF-β in ovarian cancer and dermal fibroblasts, and IL-6 in hepatoblastoma cells." (PMID 28423611, 2017). "In our study, we found that JWH-015 also inhibited EGF-induced NF-kB activation in ERα- breast cancer cells." (PMID 27213582, 2017). "The upregulation of p21 by BMP-2 prevents EGF-induced proliferation of MDA-MB-231 breast cancer cells." (PMID 28733469, 2017). "WBP2 was firstly identified to be a novel tyrosine kinase substrate in the MCF10AT model of breast cancer, and further proved to be authentic target of Epidermal Growth Factor (EGF) signaling and Iressa." (PMID 28724435, 2017). "RAB5B has been shown to be activated in malignant melanoma, while RAB5C enhances epidermal growth factor-induced progression of breast cancer." (PMID 28103577, 2017). "For further characterization, we selected the MDA-MB-231 breast cancer cell line because these cells are highly metastatic and induce cell migration upon EGF stimulation." (PMID 29212252, 2017). "There is also evidence of Epidermal Growth Factor (EGF) signalling enhancing NF-κB activity in breast cancer." (PMID 28536364, 2017). "CTX-III inhibits the EGF-induced EMT in breast cancer cells, reducing EGFR phosphorylation and activation PI3K/Akt and ERK1/2." (PMID 29189742, 2017).
breast carcinoma (continued). "The aim of this study was to clarify the regulatory mechanism underlying transcriptional activation of the CCR1 gene in response to epidermal growth factor (EGF) stimulation in breast cancer cells." (PMID 29212252, 2017). "The nine-gene set is regulated by estrogen, ERBB2 and EGF signaling, all established breast cancer factors." (PMID 28411283, 2017). "First, we analyzed the effect of CNR2 specific agonist on EGF-induced tumorigenic events in ERα- breast cancer cells." (PMID 27213582, 2017). "Following CNR2 activation, we observed inhibition of breast cancer growth, suppression of EGF/EGFR as well as IGF-I/IGF-IR signaling pathways and their related tumorigenic events in vitro and in vivo." (PMID 27213582, 2017). "SKBr3 HER2+ breast cancer cells in different wells of the 96-well biosensor were stimulated with EGF or NRG1b." (PMID 28302091, 2017). "In vitro mammosphere formation assays support a role for phospho-Ser294-PRs via growth factor (EGF) signaling as well as RUNX2 as potent drivers of breast cancer stem cell fate." (PMID 28412963, 2017). "In conclusion, we show that CNR2 activation suppresses breast cancer through novel mechanisms by inhibiting EGF/EGFR and IGF-I/IGF-IR signaling axes." (PMID 27213582, 2017). "The growth of estrogen-independent breast cancer MDA-MB-468 cells—which overexpress the EGF receptor (EGFR)—is inhibited by EGF; this is accompanied by the increased expression of some genes, including c-myc." (PMID 28417908, 2017). "Upon treatment with EGF, fibroblastic cells or mammary tumor cells overexpressing EGFR and ErbB2 undergo apoptosis in a p38-dependent manner." (PMID 28417908, 2017). "Recently, we reported that ZER abolishes CD44 expression through the inhibition of EGF/STAT-3 pathway in breast cancer cells." (PMID 26637807, 2016). "Epidermal growth factor (EGF) is well known to stimulate proliferation of human breast cancer cells in cultures." (PMID 27564112, 2016). "Aberrant EGF and its receptor EGFR (ErbB-1) signaling has been extensively described as a major cause of progression and metastasis of breast cancer." (PMID 27829223, 2016). "Taken together, these experiments demonstrated that RAB35 was required for EGF-induced invasion in breast cancer cells." (PMID 27430308, 2016). "EGF can induce EMT in a variety of tumor cells including breast cancer cell (EGF 50 ng/ml), ovarian cancer and (EGF 10 ng/ml), cervical cancer cell (EGF 50 ng/ml)." (PMID 27863382, 2016). "To verify that both Src and Abl kinases are required for breast cancer invasion toward EGF, we tested the invasiveness of MDA-MB-231 cells with and without incubation with the Src and Abl inhibitors Dasatinib or STI571." (PMID 26996666, 2016). "To uncover the potential involvement of lncRNAs in breast cancer metastasis, we first studied transcriptional responses of lncRNAs to EGF stimulation." (PMID 27485121, 2016). "Previously, we described that shrew-1 is present in protein complexes together with proto-oncogene SRC and epidermal growth factor (EGF) receptor tyrosine kinase HER-2 in MCF-7 breast cancer cells after growth factor stimulation with EGF." (PMID 27870635, 2016). "HRG can also activate anchorage-independent breast cancer cell growth more potently than EGF, whilst the HRG-dependent activation of phosphatidylinositol-3-kinase (PI3K)/Akt pathway is a necessary event for cell transformation." (PMID 26716646, 2016). "Taken together, our data suggest that, in breast cancer cells, Lpd depletion reduces EGF-elicited lamellipodial protrusion formation and persistence, but not speed." (PMID 26996666, 2016). "The 3E10 antibody also significantly inhibited the in vitro growth of HRG- and EGF-stimulated breast cancer cells." (PMID 26999718, 2016).